BID (BH3 interacting domain death agonist)
Diseases named in the same sentence as BID in open-access papers (continued):
Sharing a sentence is not in itself a finding about the gene and the disease.
tumor (continued). "Knock down of the toxic BH3 domain protein BID, which is downstream of CD95, FADD and pro-caspase 8, significantly reduced the ability of regorafenib alone or in combination with aramchol to cause autophagosome and autolysosome formation and to kill tumor cells." (PMID 40827882, 2025). "However, there is limited information as to whether BID phenocopies the tumor suppressive properties of caspase-2." (PMID 33425918, 2020). "In biological experiments, AURKA, BID, and PLA2G6 functioned as tumor promoters by enhancing the proliferation and migration of ccRCC cells." (PMID 40271062, 2025). "Our findings revealed that EZH2, AURKA, BID, PLA2G6, and EPAS1 exhibited significantly elevated expression levels in ccRCC tumor tissues compared to normal tissues." (PMID 40271062, 2025). "Accordingly, we found that apoptotic molecules downstream of T cell–mediated tumor killing were increased post-sotigalimab, including CASP3 and BID and the proapoptotic factor BAD." (PMID 38181044, 2024). "Combined with our research results, we speculate that the up-regulation of BID may regulate the internal energy metabolism of ccRCC by hindering the insulin signaling pathway, thereby increasing the demand for tumor biosynthesis and leading to tumor progression." (PMID 38767695, 2024). "Besides, the samples with high expression of BID had higher immune score, stromal score and ESTIMATE score (P < 0.001), indicating that the tumor tissue with high expression of BID may have higher content of immune cells and stromal cells, and higher tumor purity." (PMID 38767695, 2024). "The fate of tumor cells after SAC abrogation is driven by an AURKB/ CASP-2 signaling mechanism, regulated by BID levels." (PMID 37443114, 2023). "Quantitative confocal immunofluorescence analysis showed that tumor stem cell marker CD44 was significantly decreased, and the apoptotic marker BID protein expression was increased in CHCP-treated tumor samples compared to untreated tumor samples." (PMID 37509349, 2023). "Then, we prospectively tested 96 FFPE tumor samples of different histologies by RT-Q-PCR; together with FFPE blocks of 11 cell lines of known BID status." (PMID 37443114, 2023). "Here, we demonstrate that BID levels regulate an AURKB/CASP-2 mitotic checkpoint that determines the fate of tumor cells when the SAC is overridden; senescence if BID expression is low but cell death in case of high BID levels." (PMID 37443114, 2023). "BID, NAMPT, and BIRC5 were detected with the same results in tumor tissues and with adjacent normal kidney tissues, while CANX was not significantly different." (PMID 34988121, 2021). "We found that the expression levels of CANX, BIRC5, BID, and NAMPT in tumor tissues were significantly higher than their expression levels in normal tissues, indicating that they are all significantly related to tumor occurrence and development." (PMID 34988121, 2021). "However, active effectors (BAX and BAK) or initiator (PMAIP1, BIK and BID) cannot lead to apoptosis in tumours, and these pro‐apoptotic proteins may be sequestered by guardians (BCL2 and BCL2L1) that have more potent enhancer activity to propel the anti‐apoptotic mechanisms." (PMID 32419250, 2020). "In this context, massive BSB-induced BID translocation would disengage the activator BIM from its binding partners or directly activate the effectors BAK/BAX, successfully overwhelming tumor anti-apoptotic reserves." (PMID 31767857, 2019). "We have also observed activation of proapoptotic proteins, BID and t-BID following treatment with MESB compared to untreated tumor tissues suggesting the induction of apoptosis in tumor cells in mice." (PMID 23071702, 2012). "It was investigated that BID protein is downregulated in HCC when compared to normal liver tissues due to the imbalance between enhanced anti-apoptotic proteins and a reduced number of pro-apoptotic proteins that facilitate tumor cell proliferation." (PMID 39735355, 2024).
tumor (continued). "In addition, 10 kinds of immune cells in TME were related to the expression of BID, including T cells CD8, Tregs, macrophages M0 and T cells follicular helper, which were closely related to tumor." (PMID 38767695, 2024). "Firstly, our observation that BID expression interferes with tumor cell migration without affecting proliferation merits further exploration." (PMID 39023752, 2024). "Regarding BID upregulation, COSMIC reports 445/9087 (5%) tumor samples as BID overexpressors." (PMID 37443114, 2023). "In addition, the response of CANX, BID, NAMPT, and BIRC5 with different expression levels to immune checkpoint inhibitors was predicted based on Tumor Immune Dysfunction and Exclusion (TIDE) algorithm." (PMID 34988121, 2021). "BID played a similar role by activating BAX/BAK 25 and ERBB2, also known as HER2, was a member of the human epidermal growth factor receptor family, promoting cell proliferation, survival, and playing an important role in the occurrence and development of tumor." (PMID 32780567, 2020). "Thus BID does not appear to play a major role in the commitment to apoptosis during replication stress in the tumour cells tested here." (PMID 19119425, 2009). "Based on these published data and the results presented thus far; we hypothesized that SAC-targeting drugs activate CASP-2 in tumor cells and ultimately trigger CASP-3 mediated apoptosis or aneuploidy/polyploidy and survival, the balance between the two outcomes being determined by BID levels." (PMID 37443114, 2023). "Moreover, we analyzed the correlation among four-gene signature (FeSig) (BID, TAZ, MT1G, and SLC7A11), downstream hub genes (CPNE7, WNT10B, ADAMTS14, and RUFY4), and immune checkpoints (PD-1, CTLA4, LAG3, and TIGIT) to further discover potential molecular mechanisms of tumor immunity." (PMID 34367965, 2021). "Aberrant methylation is a specific characteristic of HRK in various tumor cells that is not seen in other BH3- only family genes (BAD, BID, and PUMA) examined." (PMID 27478805, 2016).
infection (28 papers, 2008 to 2025). The state of being infected such as from the introduction of a foreign agent such as serum, vaccine, antigenic substance or organism. "As BID requires proteolytic processing in order to activate its apoptotic function, infection with adenoviral vector that delivers a transgene encoding the engineered BID molecule was demonstrated to induce activation of apoptosis in cells expressing the HCV NS3 protease." (PMID 22359682, 2012). "Casp1–/– BMMs retain the ASC to caspase-8 pathway; and indeed, we observed weak caspase-8, BID, and caspase-3 cleavage at 4 hr post-infection (hpi), indicating that this pathway is relatively slow." (PMID 38055781, 2023). "Further, only Gsdmd–/– BMMs displayed release of cytochrome c from the mitochondria to the cytosol during infection, as expected by faster signaling from caspase-1 to BID." (PMID 38055781, 2023). "The expression of cell death and apoptosis-associated genes (e.g., BID, BIRC3 and PARP14) increased throughout the infection, suggestive of increased cell death in response to the infection." (PMID 34452468, 2021). "These single-mutant cells all exhibited a similar pattern of infection with either virus comparable to WT settings, demonstrating that, individually, BID, BIM, PUMA, or BOK are dispensable for suppression of ∆vMIA/vIBO-driven, BAX/BAK-mediated PCD." (PMID 34578288, 2021). "As a result, they demonstrated the induction of pro-apoptotic genes, such as RIPK2, BID, and tBID after infection." (PMID 26803467, 2016). "The induction of pro-apoptotic genes, such as RIPK2, BID and tBID was seen after infection with all three isolates, however apoptotic pathways were affected to a lesser degree by Mah 1655 than by Maa 1794 and Mah VI101." (PMID 24450835, 2014). "The protein levels of Bad, Bim, PUMA and BID almost remained constant during the infection time course." (PMID 18769617, 2008). "BAX/BAK-interacting partners BID, BIM, and PUMA are individually dispensable but contribute together, consistent with the potential diversity of BAX and BAK activators as infection progresses." (PMID 34578288, 2021). "The cleavage of BID and activation of caspase-9 and -3 were reduced in macrophages pretreated with the caspase-8 specific inhibitor (Z-IETD-FMK) prior to Mtb-infection compared with untreated cells." (PMID 27552917, 2016). "Pro-apoptotic molecules XAF1, BID, cyto c, CASP10, AIFM2, were significantly up-regulated after infection with N-PRRSV, which may induce apoptosis of virus-infected cells." (PMID 20614006, 2010). "By repressing the expression of MAPK14 and BID via miRNAs, HCV may be able to hinder apoptosis before ensuring successful establishment of virus replication at an early stage of infection." (PMID 19671175, 2009). "Given the recognized crucial functions of BID, BIM, PUMA, and BOK in activating BAX/BAK-dependent cell death, we assessed viability and viral titer in WT compared to Bid−/−Bim−/−Puma−/− as well as Bid−/−, Bim−/−, Puma−/−, and Bok−/− BMDM during infection with K!81 or ∆M38.5/M41.1 viruses." (PMID 34578288, 2021). "By contrast, the protein levels of BCL-2, BCl-XL, BAX, BAK, BIM, and BID, as well as mRNA levels of BAX, were not affected by SAMHD1 expression or HIV-1NL4-3 infection of THP-1 cell lines." (PMID 40434097, 2025). "Moreover, screening the network interactions among the genes involved in cell death/survival for both the LV and Lena strains showed that the canonical apoptosis pathway signals (BID, CASP8, MCL1 and NFKB) were activated upon LV infection, but not following Lena infection." (PMID 24643046, 2014).
bacterial infection (4 papers, 2018 to 2022). "The present study confirms that the antiapoptotic protein BIRC2 negatively regulates bacterial infection, which is consistent with our recent report showing that proapoptotic protein BID positively regulates bacterial infection." (PMID 34887869, 2021). "BID is required to activate host defense mechanisms to control bacterial infections but may also exacerbate immune-mediated inflammatory disease." (PMID 35806122, 2022). "Fas ligand (FASL/CD95L) has been shown to induce neutrophil apoptosis, which is accelerated by the processing of the BH3-only protein BH3 interacting domain death agonist (BID) to trigger mitochondrial apoptotic events, and been attributed a regulatory role during viral and bacterial infections." (PMID 29495595, 2018).
diseases of the nervous system (2 papers, 2016 to 2021). "Moreover, during the exploration of the antiapoptotic properties of Pur in diseases of the nervous system, attention has rarely focused on the relationship between the Fas/FasL and mitochondrial pathways, especially regarding the critical role of BID." (PMID 34356602, 2021).
cardiac disease (1 paper, 2018). "We propose that loss of Bid or decreased BID gene expression contributes to cardiac diseases, particularly MI." (PMID 30281024, 2018). "In sum, we have identified a homeostatic role for Bid in the regulation of mitochondrial structure and function extending initial observations in tissue culture to an in vivo model that converges on a unique role for BID in human cardiac disease." (PMID 30281024, 2018). "BID’s role in cardiac diseases is further validated through an investigation of additional independent cohorts including the large-scale CARDIoGRAMplusC4D GWAS datasets." (PMID 30281024, 2018). "PrediXcan analysis of BID expression reveals a novel role in cardiac diseases." (PMID 30281024, 2018).
colorectal (1 paper, 2025). "In colorectal carcinogenesis, miR-20a regulates BID, a gene associated with apoptosis, and affects sensitivity to TRAIL, a TNF superfamily member that induces exogenous apoptosis." (PMID 40693022, 2025).
hematological malignancies (1 paper, 2024). "BID belongs to the BCL-2 family of cell death regulators which have recently become extremely promising therapeutic targets in hematological malignancies, including MM, with the prime drug venetoclax." (PMID 39164264, 2024).
immune diseases (1 paper, 2024). "In addition, genes related to immune diseases (e.g., BID, SMARCD3, ATP6V1E1, NFKB2), energy metabolism (e.g., HAO1, NDUFA7, CERS4, MTHFD1), and other factors were also screened." (PMID 38750582, 2024).
BID also shares sentences with these, for which no sentence is quoted: Hypertension (4 papers); neuroblastoma (4); cat-eye syndrome (3); promyelocytic leukemia (3); brain tumor (2); neurodegenerative disease (2); renal cell carcinoma (2); adenoma (1); amyloid (1); anaplastic thyroid carcinoma (1); Ascites (1); Autoimmunity (1); B-cell lymphomas (1); bladder tumor (1); Burkitt lymphoma (1); cervical carcinoma (1); chronic myelogenous leukemia (1); colorectal adenoma (1); diabetic nephropathy (1); fibrosarcoma (1); gastric tumor (1); gestational diabetes (1); HIV-1 infection (1); inflammation (1); ischemic heart disease (1); lung adenocarcinoma (1); medullary carcinomas (1); medulloblastoma (1); migraine (1); mucinous adenocarcinoma (1).
A further 14 diseases each share a sentence with BID in 1 paper.